ANTXR1 (ANTXR cell adhesion molecule 1)
Description:
Plays a role in cell attachment and migration. Interacts with extracellular matrix proteins and with the actin cytoskeleton and thereby plays an important role in normal extracellular matrix (ECM) homeostasis. Mediates adhesion of cells to type 1 collagen and gelatin, reorganization of the actin cytoskeleton and promotes cell spreading. Plays a role in the angiogenic response of cultured umbilical vein endothelial cells. May also act as a receptor for PLAU. Upon ligand binding, stimulates the phosphorylation of EGFR and ERK1/2. (Microbial infection) Acts as a receptor for protective antigen (PA) of B.anthracis. (Microbial infection) Mediates cell entry of Seneca Valley virus (SVV) when glycosylated.
Synonyms: ATR; TEM8; FLJ21776; FLJ10601; GAPO
Tractability: Antibody: UniProt places it where antibodies can reach, with high confidence; its Gene Ontology location is reachable by antibodies, with high confidence; UniProt predicts a signal peptide or a membrane-spanning region. PROTAC: ubiquitination databases record sites on it.
Gene: Protein-coding gene on chromosome 2 (69,013,176 to 69,249,327, forward strand). Ensembl gene ENSG00000169604.
Subcellular location: Cell membrane; Cell projection, lamellipodium membrane; Cell projection, filopodium membrane
Subcellular location (Human Protein Atlas): Vesicles
Pathways (Reactome):
Disease: Uptake and function of anthrax toxins
Gene Ontology:
Molecular function: actin filament binding; collagen binding; protein binding; signaling receptor activity; transmembrane signaling receptor activity
Biological process: actin cytoskeleton organization; positive regulation of epidermal growth factor receptor signaling pathway; substrate adhesion-dependent cell spreading
Cellular component: cell surface; external side of plasma membrane; filopodium membrane; lamellipodium membrane; plasma membrane; endosome membrane; membrane
Genetic constraint (gnomAD): Loss-of-function variants: 19 observed, 80.48 expected, observed/expected ratio (o/e) 0.24, 90% interval 0.16 to 0.35. The upper end of that interval is the gene's LOEUF score, 0.35, which puts it in group 1 of 6, group 1 being the genes least tolerant of losing a copy. Missense variants: 513 observed, 724.87 expected, observed/expected ratio (o/e) 0.71, 90% interval 0.66 to 0.76. Synonymous variants: 270 observed, 263.42 expected, observed/expected ratio (o/e) 1.02, 90% interval 0.93 to 1.13.
Gene-disease validity (ClinGen):
ClinGen rates the evidence that ANTXR1 causes each of these diseases.
GAPO syndrome (autosomal recessive): Definitive.
Homologues: Orthologues: chimpanzee ANTXR1 (99% identical), guinea pig ANTXR1 (98% identical), dog ANTXR1 (96% identical), rat Antxr1 (96% identical), mouse Antxr1 (96% identical), rabbit ANTXR1 (91% identical), macaque ANTXR1 (90% identical), pig ANTXR1 (84% identical), tropical clawed frog antxr1 (78% identical), zebrafish antxr1b (68% identical), zebrafish antxr1a (63% identical). Paralogues in human: ANTXR2 (48% identical), ANTXRL (33% identical).
Diseases named in the same sentence as ANTXR1 in open-access papers:
ANTXR1 is named in the same sentence as 87 diseases in open-access papers, as found by Europe PMC text mining. Sharing a sentence is not in itself a finding about the gene and the disease. The quoted sentences say what the papers report.
breast cancer (29 papers, 2011 to 2025). A primary or metastatic malignant neoplasm involving the breast. "Previous reports indicated that ANTXR1 is highly expressed in breast cancer tissues and is associated with prognosis." (PMID 32401299, 2020). "The ANTXR1 is expressed on metastatic breast cancer stem cells (CSCs) and functions in collagen signaling, as well as Wnt signaling, ZEB1 expression, and CSC self-renewal, invasion, tumorigenicity, and metastasis." (PMID 36769365, 2023). "TEM8/ANTXR1 has been developed as a target in CAR-T therapy in breast cancer." (PMID 36090051, 2022). "As Tcf7l2, Antxr1/Tem8, and Arhgap18 have been associated with human breast and other cancers, these data demonstrate that MMTV-induced insertional mutation remains an important means for identifying genes involved in breast cancer." (PMID 22087314, 2011). "Overexpression of ANTXR1 activates key genes for cell proliferation, DNA replication, and WNT signalling pathways, giving increased tumorigenic and metastatic potential to breast cancer cells." (PMID 35563449, 2022). "Higher expression of the endothelial marker ANTXR1 was found on the cell surface of CD44+CD24− and ALDH1+ of the TMD231 breast cancer cell line." (PMID 35563449, 2022). "ETP binds to TEM8/ANTXR1 and Neuron-glial antigen 2 (NG2) to induce AKT and WNT signaling in cancer cells, subsequently promoting mammary tumor progression." (PMID 36428776, 2022). "Tumor Endothelial Marker 8 (TEM8), also known as Anthrax Receptor 1 (ANTXR1), is highly up-regulated in the tumor endothelium and is expressed in many cancer types, including breast cancer and CRC." (PMID 30046396, 2018). "Here, we used a high throughput approach to identify additional CISs in MMTV-induced mammary tumors and found several novel MMTV target genes including Arhgap18, Tcf7l2, Prkaca and Antxr1/Tem8 (called Antxr1 from here-on)." (PMID 22087314, 2011). "By this way, we confirmed that ANTXR1 expression and the proportion of ANTRX1+ CAF-S1 were reduced following chemotherapy in an independent cohort of HGSOC patients (Turku cohort), as well as in BC, strengthening the validity of our observations both in ovarian and breast cancer." (PMID 38346978, 2024).
anthrax (12 papers, 2011 to 2025). "In cases of anthrax infection, the binding of anthrax toxin to cell-associated ANTXR1 can result in its release into the bloodstream, leading to detectable levels of soluble ANTXR1 in the serum." (PMID 37894120, 2023). "While the direct correlation between serum ANTXR1 levels and anthrax infection remains a subject of ongoing research, our findings contribute valuable data that can inform and guide future investigations in this area." (PMID 37894120, 2023). "The presence of serum ANTXR1 levels has been identified as a potential indicator for assessing the correlation between its existence and the occurrence of anthrax infection or exposure." (PMID 37894120, 2023). "Most recently, targeted RNA interference (RNAi) technology has been used to inhibit anthrax toxin intoxication through silencing ANTXR1 and/or ANTXR2 in mouse and human macrophages." (PMID 26805886, 2016). "By generating ANTXR2-/- and ANTXR1-/- null mice, an important finding was made to reveal the differential roles of the two receptors in anthrax infection in vivo." (PMID 26805886, 2016). "The Antxr1 mutant mice were used to evaluate receptor-mediated anthrax pathogenesis, and provided definitive evidence that gene deficiency affected anthrax intoxication." (PMID 23389402, 2013). "Antxr1-mediated vascular remodeling may play an important role in the pathogenesis of anthrax." (PMID 26785120, 2016). "ANTXR1 (or TEM8) specifically binds the nontoxic protective antigen (PA) component of anthrax toxin." (PMID 31191663, 2019). "A few months later, after 2001 anthrax attack, tumor endothelial marker 8 (TEM8) was reported as an anthrax toxin receptor, hence being named anthrax toxin receptor 1 (ANTXR1), which was followed by the identification of CMG2 as the second anthrax toxin receptor (ANTXR2)." (PMID 26805886, 2016).
colon carcinoma (11 papers, 2012 to 2022). "Interestingly, genes that are associated with colon cancer progression (ANTXR1, EFEMP2, SULF1, TAGLN, VCAN, ZEB1 and ZEB2) were upregulated in patients co-overexpressing TAZ-AXL-CTGF." (PMID 23372686, 2013). "ANTXR1 has been found to be overexpressed in various types of cancers including breast, pancreatic, gastric, and colon cancer and can promote the entrance of anthrax toxin into cells." (PMID 35480887, 2022). "TEM8, also known as ANTXR1, is a cell-surface transmembrane protein initially identified in the vascular endothelial cells of colon cancer." (PMID 34523032, 2021). "It remains to be clarified if this same pathway of lineage plasticity is also present in other tumor types expressing TEM8/ANTXR1, however it is possible the same paradigm mediates metastasis and therapy resistance in subsets of triple negative breast cancer, gastric cancer, colon cancer, and NSCLC." (PMID 36090051, 2022).
gastric cancer (11 papers, 2019 to 2026). A primary or metastatic malignant neoplasm involving the stomach. "Overexpression of ANTXR1 in gastric cancer patients was associated with poor prognosis." (PMID 35409691, 2022). "In oncology, circAFF2 acts as a molecular “sponge” that sequesters miR-6894-5p, relieving its repression of ANTXR1 and thereby facilitating gastric cancer progression." (PMID 41399379, 2026). "The TGF-beta pathway, one of the most common pathways involved in cancer, is also activated in gastric cancer and is correlated with high expression of ANTXR1." (PMID 39917181, 2024). "ANTXR1 was verified to be lowly expressed in normal tissues, but its expression increased in cancer tissues, including in individuals with gastric cancer." (PMID 35409691, 2022). "Moreover, early research has demonstrated that circ_0001947 facilitates gastric cancer progression via modulating the miR-6894-5p/ANTXR1 axis." (PMID 34528912, 2021). "Similarly, in gastric cancer high ANTXR1 expression was correlated with poor OS and PFS." (PMID 39917181, 2024).
triple-negative breast carcinoma (10 papers, 2019 to 2025). An invasive breast carcinoma which is negative for expression of estrogen receptor (ER), progesterone receptor (PR), and human epidermal growth factor receptor 2 (HER2). "Likewise, CAR T cell-based immunotherapy targeting ANTXR1/TEM8 has been developed and shown to have cytotoxic specificity for tumor endothelial cells as well as ANTXR1-positive triple-negative breast cancer cells or gastric adenocarcinoma cells." (PMID 31191663, 2019).
colorectal cancer (9 papers, 2016 to 2024). A primary or metastatic malignant neoplasm that affects the colon or rectum. "ANTXR1 is a protein coding gene located on chromosome 2, encoding the type 1 cross‐membrane protein, which is a tumor endothelial logo related to colorectal cancer." (PMID 36342317, 2022). "Antxr1, also known as Tem8, is a highly conserved cell surface protein that is a marker of tumour-associated endothelial cells versus normal endothelial cells in colorectal cancer." (PMID 37833999, 2023). "At present, most of the research on ANTXR1 is related to colorectal cancer." (PMID 36342317, 2022).
melanoma (9 papers, 2011 to 2024). A malignant, usually aggressive tumor composed of atypical, neoplastic melanocytes. "Supporting this suggestion, we also found that in the presence of higher levels of ANTXR1 in melanoma, a difficult cancer to treat, correlated with poor prognosis in terms of overall survival in patients when treated with immunotherapy." (PMID 39917181, 2024). "Targeted homologous recombination of the ANTXR1 gene resulted in impaired tumor growth of transplanted melanoma and other tumors in mouse models." (PMID 37998358, 2023). "One study showed genetic disruption of TEM8/ANTXR1 in a variety of human tumor xenograft models including melanoma, breast, colon, and lung cancer led to decreased tumor growth." (PMID 36090051, 2022). "However, Antxr1 expression is highly upregulated in the tumor endothelium, and the growth of human tumor xenografts, including melanoma, breast, colon, and lung cancer, is impaired in Antxr1–/– mice." (PMID 32244499, 2020). "It would later be confirmed that ANTXR1 is expressed on cancer cells of different tumor entities including breast, neuroblastoma, and melanoma, and neuroblastoma and melanoma xenografts are also sensitive to LeTx, highlighting the broad role that this protein may play in cancer cell biology." (PMID 31191663, 2019).
alopecia (6 papers, 2018 to 2024). Hair loss usually from the scalp. "ANTXR1 gene mutation can also cause growth retardation, alopecia, pseudo-anodontia, and GAPO syndrome (GAPOS)." (PMID 36065334, 2022). "Pathogenic variants in ANTXR1 lead to the rare GAPO syndrome, named for its four primary features: Growth retardation, Alopecia, Pseudoanodontia, and Optic atrophy." (PMID 38653789, 2024). "Mutation of Antxr1 causes GAPO syndrome, which is characterized by growth retardation, alopecia, pseudo-anodontia, and optic atrophy." (PMID 32244499, 2020). "Mutation of Antxr1 results in GAPO syndrome, which is an autosomal recessive disorder and characterized by growth retardation, alopecia, pseudo-anodontia, and progressive visual impairment." (PMID 32244499, 2020). "Homozygous and biallelic variants in ANTXR1 have been associated with Growth retardation, Alopecia, Pseudoanodontia, and Optic atrophy (GAPO) syndrome, characterized by delayed growth, alopecia, failure of tooth eruption, and optic atrophy segregating as an AR trait." (PMID 29772684, 2018).
GAPO syndrome (6 papers, 2015 to 2024). "Nonetheless, the specific mechanisms connecting ANTXR1 deficiency to the clinical manifestations of GAPO syndrome are largely unexplored." (PMID 38653789, 2024). "In this study, by examining the consequences of ANTXR1 deficiency in human fibroblasts, we shed light on the pathogenesis of GAPO syndrome." (PMID 38653789, 2024). "The mechanism of abnormal accumulation of extracellular matrix in GAPO syndrome, which is caused by Antxr1 mutation, has been well studied." (PMID 32244499, 2020). "Interestingly, we observed that ANTXR1-deficient fibroblasts, and fibroblasts from GAPO syndrome patients, displayed several characteristics associated with cellular senescence." (PMID 38653789, 2024). "In addition to DNA sequencing, mutations in ANTXR1 were confirmed by the appearance of anatomical and tissue abnormalities, similar to those found in KO mice and mutations in ANTXR1 associated with the rare disease, known as GAPO syndrome, in humans." (PMID 35322150, 2022). "Strikingly, ANTXR1 knockout (KO) pigs exhibited features consistent with the rare disease, GAPO syndrome, in humans." (PMID 35322150, 2022). "Thus, the ANTXR1-edited pigs provide a useful model for investigating GAPO syndrome in humans as the pigs more closely recapitulate the disease phenotype." (PMID 35322150, 2022). "Thus, elucidation of the regulatory mechanisms for chondrocyte proliferation and apoptosis by Antxr1 will be beneficial not only for understanding physiological skeletal development but also for clarifying the pathogenesis of GAPO syndrome, osteoarthritis, and cancer growth." (PMID 32244499, 2020). "Overall, genetic disruption of ANTXR1 in pigs provides a unique model for GAPO syndrome and prevents circulating SVA infection and clinical symptoms, confirming that ANTXR1 acts as a receptor for the virus." (PMID 35322150, 2022).
glioblastoma (5 papers, 2021 to 2024). The most malignant astrocytic tumor (WHO grade IV). "Specifically, in a recent preprint, upregulation of hypomethylated TEM8/ANTXR1 genes in glioblastomas is associated with increased proliferation, metastasis, and resistance to chemotherapy and radiotherapy." (PMID 36090051, 2022). "In glioblastomas upregulated TEM8/ANTXR1 is also a negative prognostic factor." (PMID 36090051, 2022).
optic atrophy (5 papers, 2018 to 2024). A disorder characterized by loss of optic nerve fibers. "GAPO syndrome (OMIM:230,740) is a AR disorder characterized by growth retardation, alopecia, pseudo-anodontia and frequent optic atrophy, caused by ANTXR1 variants." (PMID 35551639, 2022). "Six consanguineous Egyptian GAPO families were reported in addition to one family without optic atrophy, all presenting homozygous ANTXR1 variants." (PMID 35551639, 2022).
osteosarcoma (5 papers, 2016 to 2021). A usually aggressive malignant bone-forming mesenchymal neoplasm, predominantly affecting adolescents and young adults. "Furthermore, knockdown of Antxr1 reduced the proliferation of osteosarcoma and XWLC05 lung adenocarcinoma cells." (PMID 32244499, 2020). "Although Antxr1 knockdown was reported to reduce Ccnd1 and to increase Cdkn1a and Cdkn1b expression in osteosarcoma cells, their expression was not changed in the limb cartilage of Antxr1 tg mice compared with that in wild-type mice at E15.5 by microarray analysis (data not shown)." (PMID 32244499, 2020).
gastric adenocarcinoma (4 papers, 2019 to 2025). "In addition, ANTXR1 is regarded as a potential target for CAR T cell immunotherapies in gastric adenocarcinoma, which makes it more applicable for clinical treatment." (PMID 32695142, 2020). "TEM8/ANTXR1 has been investigated as a therapeutic target in various cancers, including gastric adenocarcinoma, showing promising preclinical results." (PMID 40849468, 2025).
pancreatic cancer (4 papers, 2019 to 2022). "We observed that ANTXR1 mRNA expression was significantly elevated in whole pancreatic tumor samples versus adjacent normal tissue and tumors of the basal subtype, having worse prognosis, expressed significantly higher levels of ANTXR1 compared to classical subtype tumors." (PMID 31191663, 2019).
prostate carcinoma (4 papers, 2016 to 2023). A carcinoma that arises from epithelial cells of the prostate gland. "The identification of TEM8/ANTXR1 as a potential mediator of neuroendocrine transformation was most clearly shown in prostate cancer, where N-MYC was found to promote dysregulated angiogenesis and tumor progression via TEM8/ANTXR1." (PMID 36090051, 2022).
glioma (3 papers, 2019 to 2023). A benign or malignant brain and spinal cord tumor that arises from glial cells (astrocytes, oligodendrocytes, ependymal cells). "In another study this miRNA inhibited malignant behavior of glioma cells by targeting ANTXR1." (PMID 36354672, 2022).
hepatocellular carcinoma (3 papers, 2018 to 2023). A malignant tumor that arises from hepatocytes. "One exception to this trend is TEM8 expression in hepatitis B (HBV)-induced hepatocellular carcinoma in which ANTXR1 is hypothesized to act as a cellular receptor for HBV and transport unknown antineoplastic therapeutics within the cell." (PMID 37998358, 2023). "In hepatocellular carcinoma (HCC) cell lines microRNA-493 suppressed tumor cell growth by targeting TEM8/ANTXR1 and R-Spondin 2 (RSPO2) and decreasing activation of the Wnt/β-catenin signaling pathway." (PMID 36090051, 2022).
hyaline fibromatosis syndrome (3 papers, 2015 to 2024). "Specifically, pathogenic variants in ANTXR2 have been associated with hyaline fibromatosis syndrome, while ANTXR1 pathogenic variants are responsible for GAPO syndrome." (PMID 38653789, 2024).
colorectal tumor (2 papers, 2009 to 2016). "Qualitatively the expression of the whole tumour samples were consistent with tumour stroma, with genes highly specific for colorectal tumour stroma (e.g., ANTXR1), and DAVID analysis identifying highly significant functional groups involved in extracellular matrix function." (PMID 19401702, 2009).
dwarfism (2 papers, 2020 to 2024). "Although Antxr1–/– mice exhibit dwarfism, the function of Antxr1 in skeletal development remains to be clarified." (PMID 32244499, 2020). "However, Antxr1 tg mice with 18 times higher Antxr1 expression exhibited dwarfism, markedly shortened limbs, small rib cage, delayed mineralization, and ectopic mineralization in tibia." (PMID 32244499, 2020).
gastric tumors (2 papers, 2019 to 2020). "Results showed that there was a significant difference in the expression of ANTXR1 between non-paired/paired gastric tumors and adjacent samples." (PMID 33385012, 2020). "However, the potential mechanisms of ANTXR1 in gastric tumor progression and cancer immunology have not been extensively studied." (PMID 33385012, 2020).